LINC02880 (long independently transcribed non-coding RNA 2880)
Synonyms: FLJ34503
Gene: Long non-coding RNA gene on chromosome 6 (113,873,551 to 113,921,642, forward strand). Ensembl gene ENSG00000175967.
Diseases named in the same sentence as LINC02880 in open-access papers:
LINC02880 is named in the same sentence as 1 disease in open-access papers, as found by Europe PMC text mining. Sharing a sentence is not in itself a finding about the gene and the disease.
LINC02880 shares sentences with these, for which no sentence is quoted: infection (1 paper).